ICAM1 (intercellular adhesion molecule 1)
Diseases named in the same sentence as ICAM1 in open-access papers (continued):
Sharing a sentence is not in itself a finding about the gene and the disease.
endothelial dysfunction (continued). "Elevated levels of intercellular and vascular adhesion molecules (ICAM1, VCAM1), which are considered markers of endothelial dysfunction, have been observed in patients with CKD." (PMID 37109198, 2023). "The expression levels of ICAM-1, VCAM-1, vWF, and ET-1 in CiGEnCs were measured to evaluate the degree of endothelial dysfunction." (PMID 37188751, 2023). "Several studies in Dahl SS and SHRs reported cytokine secretion and an overexpression of leukocyte adhesion molecules, including ICAM-1, MCP-1, and Mac-1 in events of hypertension and endothelial dysfunction development following salt intake." (PMID 37108475, 2023). "Increased endothelial expression of ICAM-1 and VCAM-1 was observed one-day post-ligation, and endothelial dysfunction was seen seven days post-ligation." (PMID 37174655, 2023). "In patients with SLE, early endothelial dysfunction is present in those subjects who have low FMD, which correlates with modified or native LDL, as well as soluble E-selectin and ICAM-1 serum levels." (PMID 36293156, 2022). "In human endothelial cells, quercetin or its metabolite isorhamnetin inhibit the expression of biomarkers of endothelial dysfunction including VCAM-1, ICAM-1 and MCP-1 at a physiologically attainable concentration of 2 μM." (PMID 35268723, 2022). "Upregulation of cellular adhesion molecules (ICAM-1 and VCAM-1), are among the phenotypic characteristics of endothelial dysfunction (VCAM-1)." (PMID 36408439, 2022). "Current evidence suggests that concomitant administration of metformin during radiotherapy in rats decreases the expression of E-selectin, ICAM-1, and VCAM-1, thereby acting as a potent heart protector from endothelial dysfunction-induced damage." (PMID 35910360, 2022). "As the main finding, this study showed that in patients with T2DM Taurine exposure for 8 weeks significantly decreased the biomarkers related to endothelial dysfunction including VCAM, ICAM-1, and MMP-9." (PMID 35870947, 2022). "Consumption of a single high-fat meal rich in saturated fatty acids can induce endothelial dysfunction in otherwise healthy subjects, as evidenced by the related increased concentrations of VCAM-1, ICAM-1, IL-6, IL-18, and TNF-α." (PMID 35268723, 2022). "Increased serum ICAM-1 and VCAM-1 suggested increased cross talk between neutrophil and endothelial cell, as well as, endothelial dysfunction." (PMID 34449018, 2022). "The adhesion molecules expressed by the endothelium, such as intercellular adhesion molecule-1 (ICAM-1) and vascular cell adhesion molecule-1 (VCAM-1), are widely accepted biomarkers of endothelial dysfunction." (PMID 34198968, 2021). "Endothelial dysfunction as measured by reflection index (RI), biomarkers of oxidative stress (NO, MDA, and glutathione), and inflammation (hsCRP, endothelin-1, ICAM-1, and VCAM-1) were evaluated at baseline, 4, and 12 weeks." (PMID 34257675, 2021). "In the current study, higher ICAM-1 could independently increase the negative risk in the achievement of response to low-dose decitabine, indicating that persistence of endothelial dysfunction might be attributable to refractory/resistance to existing ITP-specific treatments." (PMID 34326842, 2021). "In HUVECs, SIRT6 significantly promotes eNOS activity and down-regulates the expression of intercellular adhesion molecules (ICAM-1) and VCAM1 by activating Nrf2, thereby alleviating endothelial dysfunction induced by CCs." (PMID 33855020, 2021). "Following endothelial dysfunction, adhesion molecules (e.g., VCAM-1, ICAM-1 and E-selectin) and chemokines (e.g., MCP-1) trigger the recruitment of monocytes to the aortic intima." (PMID 34769040, 2021). "In this work, endothelial dysfunction was induced in HFD fed ApoE-/- mice, as demonstrated by the decrease of serum NO level as well as the increase of the adhesion molecule (E-selectin, ICAM-1 and VCAM-1) and chemokine (MCP-1) expression in the aorta." (PMID 34769040, 2021).
endothelial dysfunction (continued). "Biomarkers of endothelial dysfunction, namely vascular cell adhesion molecule 1 (VCAM-1) and intercellular adhesion molecule 1 (ICAM-1), were evaluated in the aorta." (PMID 34940528, 2021). "The anthropometric and blood indices before and after exercise were recorded and compared, and the endothelial dysfunction was evaluated by examining the levels of markers, including VCAM-1, ICAM-1, and E-selectin, using an ELISA assay." (PMID 34123418, 2021). "Increased levels of ICAM-1, VEGF, and Angiopoietin-2 were found in corticosteroid resistant ITP patients compared with healthy controls, indicating the occurrence of endothelial dysfunction in ITP." (PMID 34326842, 2021). "Endothelial dysfunction is characterized by the increased expression of adhesion molecules, such as vascular cell adhesion molecule-1 (VCAM-1) and intercellular adhesion molecule-1 (ICAM-1), allowing the accumulation of monocytes in the subendothelial matrix." (PMID 34201484, 2021). "In summary, this was the first study to elucidate the relationship between endothelial dysfunction and corticosteroid resistant ITP and identify the potential predictive value of ICAM-1 level for response to low-dose decitabine." (PMID 34326842, 2021). "ELISA kits were used to detect the levels of endothelial dysfunction (ED) markers, including vascular cell adhesion molecule 1 (VCAM-1), intercellular adhesion molecule 1 (ICAM-1) and E-selectin." (PMID 33546604, 2021). "CM has a preventive effect against endothelial dysfunction by lowering inflammatory response (through VCAM-1, ICAM-1 expression regression) and reducing caspase-mediated apoptosis." (PMID 33627181, 2021). "Fifth, the expression of adhesion molecules such as P-selectin, E-selectin, ICAM-1, and VCAM-1 is increased; these are all markers of endothelial dysfunction, and can serve as receptors for leukocytes (monocytes, neutrophils, and lymphocytes)." (PMID 34200975, 2021). "Our data showed that the mRNA expressions of vWF, ET, THBD, ICAM-1, and GMP140 were significantly increased, suggesting endothelial dysfunction." (PMID 34576058, 2021). "The presence of endothelial dysfunction in preeclampsia has been well established, which was confirmed in our cohort by increased expressions of the endothelial dysfunction markers, VCAM-1 and ICAM-1 (VCAM-1: P < 0.01; ICAM-1: P ˂ 0.001; n = 3)." (PMID 32617576, 2021). "We measured the levels of high-sensitivity C-reactive protein (hs-CRP), intercellular adhesion molecule 1 (ICAM-1), and vascular cell adhesion molecule 1 (VCAM-1) as markers of inflammation and endothelial dysfunction." (PMID 32433661, 2020). "Not surprisingly, many of the most upregulated genes are well-known markers of endothelial dysfunction (e.g., SELE, ICAM1, SOD2, IL8, IL1B)." (PMID 31287004, 2019). "Several studies have demonstrated changes in the levels of cell adhesion molecules such as ICAM1, VCAM1 and selectins in response to oxidative stress in endothelial cells which result in the progression of endothelial dysfunction." (PMID 31547324, 2019). "The levels of such markers of endothelial dysfunction (PAI-1, ADMA, VCAM-1, and ICAM-1) have also shown to be higher in PCOS patients as compared with controls." (PMID 31456040, 2019). "The present study was aimed at determining plasma levels of ICAM-1, VCAM-1 and E-Selectin as markers of endothelial dysfunction in SCD patients in steady state, complications and controls." (PMID 29690499, 2018). "Endothelial cell activation accompanies endothelial dysfunction, and is characterized by increased expression of adhesion molecules such as vascular cell adhesion molecule-1 (VCAM-1) and intercellular adhesion molecule-1 (ICAM-1)." (PMID 29337890, 2018). "The current study aimed to determine plasma levels of ICAM-1, VCAM-1 and E-Selectin as markers of endothelial dysfunction in SCD patients in steady state, complications and controls." (PMID 29690499, 2018).
endothelial dysfunction (continued). "A rise in the serum levels of cellular adhesion molecules, intercellular adhesion molecule 1 (ICAM-1), and vascular cell adhesion molecule 1 (VCAM-1) as specific markers of endothelial dysfunction indicates an impaired endothelial function." (PMID 31011351, 2018). "The high expression of adhesion molecules, such as ICAM-1 and VCAM-1, leading to an abnormal increase in adhesion ability onto endothelial cell surface, is an important feature of endothelial dysfunction." (PMID 28798687, 2017). "Dh404 significantly attenuated endothelial dysfunction in diabetic Akita mice characterized by reduced contraction in response to phenylephrine and the downregulation of inflammatory genes (VCAM-1, ICAM-1, p65, IL-1β) and pro-oxidant genes (Nox1 and Nox2)." (PMID 28253885, 2017). "Although several studies of the biomarkers of endothelial dysfunction have been done in patients with T2DM and most of them have demonstrated increased concentration of E-selectin, ICAM-1, and VCAM-1 data about the endothelial dysfunction in MCI are poor." (PMID 26167502, 2015). "ICAM-1 and VCAM-1 expression is up regulated during endothelial-dysfunction at postmenopause, a phenomenon also influenced by estrogen receptors (ERs) SNPs, contributing to systemic inflammation and endothelial damage." (PMID 25993480, 2015). "Others have found that liraglutide inhibits high-glucose induced endoplasmic reticulum stress, and also TNFα induced markers of endothelial dysfunction such as PAI-1, ICAM-1, and VCAM-1 in human umbilical vein endothelial cells (HUVECs)." (PMID 24835252, 2014). "ICAM-1 and VCAM-1 are important markers of endothelial dysfunction that have been demonstrated to play important roles in the development of diabetic retinopathy." (PMID 25287126, 2014). "ICAM-1, VCAM-1, and ET-1 are important markers of endothelial dysfunction that have been demonstrated to play important roles in the development of DRP." (PMID 24688225, 2014). "The inhibitory effects of flavonoids on oxLDL-induced endothelial dysfunction were evaluated by measuring cell viability and the level of malondialdehyde (MDA), nitric oxide (NO) and soluble intercellular adhesion molecule-1 (sICAM-1)." (PMID 22016603, 2011). "We observed elevated proinflammatory and endothelial dysfunction indices such as BKB1R, ICAM-1, and VWF expression in endothelium following LPS treatment." (PMID 19171072, 2009). "In univariate analysis, all three biomarkers of endothelial dysfunction (VCAM-1, ICAM-1 and ECAM-1) were higher in patients than in control individuals." (PMID 15899050, 2005). "We found that the biomarkers of endothelial dysfunction VCAM-1, ICAM-1 and ELAM-1 were higher in 74 RA patients than in 80 healthy control individuals." (PMID 15899050, 2005). "Moreover, cytokine-induced endothelial dysfunction results in increased vascular permeability, expression of adhesion molecules (VCAM-1, ICAM-1), and reduced NO bioavailability, thereby promoting a pro-atherogenic state." (PMID 40227756, 2025). "Another study in Iran assessed the impact of Ramadan fasting on the molecular marker of endothelial dysfunction, intercellular adhesion molecule-1 (ICAM-1), in both individuals with and without diabetes who fasted the whole month of Ramadan." (PMID 40943951, 2025). "Additionally, increased levels of cellular adhesion molecules like E-selectin, ICAM-1, and VCAM-1 in the plasma have been recognized to identify diabetes and CAD-induced endothelial dysfunction." (PMID 40072053, 2025). "To evaluate whether NAC protects against oxLDL-induced endothelial dysfunction, we assessed NO levels, eNOS and LOX-1 expression, and pro-inflammatory adhesion proteins, including ICAM-1 and VCAM-1." (PMID 40774821, 2025).
endothelial dysfunction (continued). "Moreover, in addition to the traditional cytokine-mediated endothelial activation (e.g., P-selectin, ICAM-1 upregulation), MIRI-induced ROS and NETs work in synergy to impair NO signaling, which triggers the endothelial dysfunction and leukocyte adhesion." (PMID 40722608, 2025). "Acute exposure to ambient PM2.5 pollution may lead to a substantial increase in key markers of endothelial function, such as ICAM-1, VCAM-1, and selectins indicating potential endothelial dysfunction as a result of exposure to ambient air pollution." (PMID 40149705, 2025). "Elevated levels of IL-6, TNF-alpha, CRP, MCP-1, and endothelial dysfunction biomarkers such as oxidized HDL and soluble ICAM-1 supports the role of inflammation in the development and persistence of visceral adiposity and systemic inflammation in this population." (PMID 40722634, 2025). "This activation is particularly pronounced in severe COVID-19 cases, leading to elevated levels of soluble ICAM-1 (intercellular adhesion molecule 1) and VCAM-1 (vascular cell adhesion molecule 1), which contribute to endothelial dysfunction and multiorgan damage." (PMID 40416618, 2025). "Both sexes had increased circulating plasminogen activator inhibitor-1 (PAI-1), higher PAI-1 gene expression in VAT and PVAT, and elevated intercellular adhesion molecule-1 (ICAM-1) gene expression in the aorta, contributing to endothelial dysfunction in the HHTg strain." (PMID 39858414, 2024). "Biochanin A possibly prevents endothelial dysfunction via a complex network structure with multiple targets and pathways, among which AKT1, TNF-α, NOS3, ICAM-1, and VCAM-1 may be the key targets, according to network pharmacological analysis results." (PMID 38195507, 2024). "We did not record associations of serum leptin with endothelial dysfunction, but we followed only FMD and not molecules such as vascular cell adhesion protein 1 (V-CAM 1) and intercellular adhesion molecule 1 (I-CAM 1), as in other studies." (PMID 39062887, 2024). "AKT1, TNF-α, VCAM1, ICAM1, and NOS3 might be the key targets of the anti-endothelial dysfunction activity of biochanin A, and the key pathways might be PI3K-Akt and TNF signaling pathways." (PMID 38195507, 2024). "Also, high AUC for Ang 2:Ang1, Ang 2:Tie 2, ICAM1:VCAM-1, and VEGFA: Ang 2 ratios suggest endothelial dysfunction and instability, key factors in SCD and angiogenesis." (PMID 39749215, 2024). "Markers of endothelial dysfunction may provide more insight into the role of endothelial impairment driving the disease stages; markers include VCAM1, ICAM1, and ET-1." (PMID 37893034, 2023). "Furthermore, exposure to HG + IS led to upregulation of adhesion molecules SELE, VCAM1, ICAM-1 in HUVEC, while incubation of DKD-MSCcm attenuated mRNA expression, suggesting that DKD-MSCcm prevents endothelial dysfunction." (PMID 36949528, 2023). "Furthermore, fibrinogen triggers the development of endothelial dysfunction by increasing the expression of adhesion molecules like VCAM-1 and intercellular adhesion molecule 1 (ICAM-1) which promote the expression of NF-κB." (PMID 37442896, 2023). "Adhesion molecules such as intercellular adhesion molecule 1 (ICAM-1) and vascular cellular adhesion molecule 1 (VCAM-1) can be released into circulatory system when vasculature is damaged, accompanied by vascular inflammation and endothelial dysfunction." (PMID 36710676, 2023). "For example, saxagliptin attenuates ox-LDL-induced cytokine and vascular adhesion molecule (TNF-α, Il-1β, ICAM-1, VCAM-1) production by inhibiting AP-1 and NF-κB and reduces Nox4 expression, thereby inhibiting the excessive generation of ROS and improving endothelial dysfunction." (PMID 37660030, 2023).
endothelial dysfunction (continued). "TNF-α induces migration and proliferation of smooth muscle cells from the medial side of the vessel wall to the intima through upregulation of intercellular cell adhesion molecule-1 (ICAM-1), scavenger receptor class A and MCP-1 expression, ultimately leading to endothelial dysfunction." (PMID 37822930, 2023). "In addition, TDI01 rescued endothelial dysfunction by downregulating the expression of VCAM1 and ICAM1, attenuating inflammatory cell adhesion and decreasing permeability." (PMID 36969192, 2023). "In addition, AGEs accumulate in atherosclerotic lesions contributing to endothelial dysfunction and up-regulating the expression of vascular cell adhesion molecule-1 (VCAM-1) or intercellular adhesion molecule-1 (ICAM-1)." (PMID 36985650, 2023). "Several studies have assessed endothelial dysfunction usingflow-mediated dilatation (FMD), nitroglycerin-mediated dilation (NMD), andbiomarkers (E-selectin, P-selectin, intercellular adhesion molecule-1 (ICAM-1),and vascular cellular adhesion molecule-1 (VCAM-1))." (PMID 39076622, 2022). "Furthermore, in conditions of endothelial dysfunction, NO bioavailability is often reduced in relation to increased expression of VCAM‐1 and ICAM‐1 through enhanced reactive oxidative stress in the vessel walls." (PMID 36301720, 2022). "RT-PCR of liver sinusoidal endothelial cells showed a markable increment of von Willebrand Factor (vWF), thrombomodulin(TM), intercellular adhesion moleclar-1(ICAM-1), and vascular endothelial growth factor(VEGF) after TGF-β1 treatment, suggesting the involvement of endothelial dysfunction." (PMID 36225950, 2022). "ox-LDL-induced LOX-1 activation triggers endothelial dysfunction and the expression of atherosclerotic inflammatory genes, such as monocyte chemotactic protein 1 (MCP-1), intercellular adhesion molecule 1 (ICAM-1), and vascular cell adhesion molecule 1 (VCAM-1) in ECs." (PMID 35402552, 2022). "Also, by downregulating ICAM-1 and VCAM-1, kaempferol can ameliorate endothelial dysfunction and rheumatic disease symptoms." (PMID 36267087, 2022). "TSA prevented the up-regulation of the endothelial dysfunction markers (VCAM-1 and ICAM-1)." (PMID 36362263, 2022). "Moreover, this cytokine induces expression of the soluble adhesion molecules ICAM-1 and VCAM-1, markers of endothelial dysfunction." (PMID 35050236, 2022). "The natural progression of DM is hyperglycemia, which contributes to oxidative stress, and pro-inflammatory markers, which lead to lipid peroxidation, increase the oxidative stress scenario, resulting in inflammation and increased VEGF, ICAM-1, VCAM-1, endothelial dysfunction, and apoptosis." (PMID 34012421, 2021). "Indeed, vascular cell adhesion molecule 1 (VCAM-1) and intercellular adhesion molecule 1 (ICAM-1) play an important role in the initiation of inflammation and endothelial dysfunction." (PMID 34940528, 2021). "Furthermore, increased gene expression of vascular inflammation-related specific adhesion molecules ICAM-1 and VCAM-1 following IR injury, reflecting endothelial dysfunction, has been lessened by CM." (PMID 33627181, 2021). "In this study, the expression levels of MALTA1 and miR-320a in obese children and adolescents before and after exercise were examined, and their correlation with endothelial dysfunction was investigated by evaluating the levels of VCAM-1, ICAM-1, and E-selectin." (PMID 34123418, 2021). "In our study, we demonstrated that down-expression of ICAM-1 by CANA in aortic rings submitted to in vitro IRI (i.e., in the absence of leucocyte binding) was associated with less endothelial dysfunction." (PMID 34360539, 2021). "Intercellular adhesion molecule 1 (ICAM-1) and vascular cell adhesion molecule 1 (VCAM-1) are also important factors in the development of endothelial dysfunction and atherosclerotic plaque formation, by facilitating the transmission of leukocytes through the epithelium and their adhesion." (PMID 34685718, 2021).